BCL2 (BCL2 apoptosis regulator)
Diseases named in the same sentence as BCL2 in open-access papers (continued):
Sharing a sentence is not in itself a finding about the gene and the disease.
myocardial infarction (66 papers, 2011 to 2025). Gross necrosis of the myocardium, as a result of interruption of the blood supply to the area, as in coronary thrombosis. "Previous research demonstrated that cardiomyocyte apoptosis caused by acute myocardial infarction resulted in a decrease in the bcl-2/bax ratio and expression of p-JAK2 and p-STAT3, while the expression of p-JAK2 and p-STAT3 protein increased significantly." (PMID 37567042, 2023). "In a rat model of MI, C1-INH caused the reversal of the Bcl-2/Bax expression in the myocardial infarct area." (PMID 24877121, 2014). "There may be a mechanistic association with the up-regulation of the Bax/Bcl-2 ratio in the myocardium after myocardial infarction with depression." (PMID 23394076, 2013). "The anti-apoptotic properties of carvacrol have been shown to modulate the expression and protein levels of Bcl-2, Bax, and caspase-3 in animal models with hypertrophic heart and acute myocardial infarction." (PMID 40292260, 2025). "Bcl2 inhibits cell apoptosis, and animal experiments showed that apoptosis occurred in acute myocardial infarction, accompanied by decreased expression of Bcl2." (PMID 39388704, 2025). "Sevoflurane treatment during early reperfusion led to a marked reduction in myocardial infarct size and cleaved caspase-3 expression, and increased Bcl-2 protein expression." (PMID 39093878, 2024). "Due to myocardial I/R, STAT3 upregulates the expression of Bcl-2, Bcl-xl, and other genes, which have been shown to reduce cell death and lessen adverse cardiac remodeling after myocardial infarction." (PMID 36969839, 2023). "Many studies suggested that benfotiamine, a thiamine derivative, improves post-myocardial infarction and increases the Bcl-2 protein levels." (PMID 37427326, 2023). "Myocardial Notch1 level is activated after injury and enhances the anti-apoptotic signaling Akt and Bcl-2 and improves heart function after myocardial infarction." (PMID 36036015, 2022). "GSK-3β-specific deficiency dramatically inhibits apoptosis after myocardial infarction (MI), and conditional deletion of GSK-3α in the heart reduces the Bax/Bcl-2 ratio and apoptosis." (PMID 36036015, 2022). "In an acute myocardial infarction rat model, miRNA-15b was demonstrated to deteriorate cardiomyocyte apoptosis by post-transcriptionally down-regulating the expression of BCL-2 and MAPK3." (PMID 33706714, 2021). "In particular, Ex-4 pretreatment in models of myocardial infarction and subarachnoid hemorrhage downregulates apoptosis by inhibiting the release of cytochrome c via Bax/Bcl-2 regulation." (PMID 34685508, 2021). "From these findings in experimental studies, miR-135a and miR-486 are thought to work oppositely regarding the Bcl-2-regulated apoptotic pathway in remodeling post myocardial infarction." (PMID 32788621, 2020). "This indicates that baicalin can up-regulatethe expression of the Bcl-2 protein and down-regulate the expression of the Baxprotein in rats, thus mitigating the myocardial infarction." (PMID 30184036, 2018). "In this study, we confirmed that S-post activated the JAK2–STAT3 signaling pathway, upregulated Bcl-2 protein levels, and inhibited Bax protein levels, ultimately inhibiting cardiomyocyte apoptosis and reducing myocardial infarct size." (PMID 28392989, 2017). "The I/R aggravated cardiomyocytes damage, apoptosis and myocardial infarct size, reduced cardiac function, increased the level of Bcl-2, caspases-3 and caspase-9 mRNA, the mitochondrial release of Cyt c and oxidative stress in the aging hearts." (PMID 25789157, 2015). "Specifically, diabetic mice subjected to myocardial infarction (MI) overexpress ICER protein which reduces antiapoptotic Bcl-2 levels thus leading to apoptosis." (PMID 24868554, 2014). "Cardiac-specific overexpression of the anti-apoptotic regulator Bcl-2 substantially reduces infarct size, cardiac myocyte apoptosis and cardiac dysfunction following myocardial infarction." (PMID 23592614, 2013).
myocardial infarction (continued). "Up-regulation of the Bax/Bcl-2 ratio can induce greater apoptotic activity, suggesting that there was greater vulnerability to apoptosis of myocardial cells with acute myocardial infarction with comorbid major depression." (PMID 23394076, 2013). "Previous studies also showed that MSCs reduced cardiomyocyte apoptosis and increased the Bcl-2 to Bax protein ratio in myocardial infarction." (PMID 23508361, 2012). "Ligation of the left anterior descending coronary artery in dogs for 1 hour then 6~72 hours reperfusion have resulted in a reduction Bcl-2 and increase of Bax expression with the corresponding myocardial apoptosis and myocardial infarction." (PMID 21600015, 2011). "Previous studies have indicated that the inhibition of Bax activity and promotion of Bcl-2 expression could confer a direct cardioprotective effect in acute myocardial infarction." (PMID 40427461, 2025). "Additionally, following myocardial infarction, the expression of caspase 3 and Bax, key regulators of apoptosis, were significantly upregulated, while the expression of Bcl-2 was markedly decreased." (PMID 40471885, 2025). "Phorbol-12-myristate-13-acetate-induced protein 1 (Pmaip1), a BCL-2 protein is essential to apoptosis, regeneration and disease pathways.In an animal model of myocardial infarction/reperfusion, Pmaip1 and BimEL protein levels were elevated after 3 hours of reperfusion." (PMID 41234537, 2025). "The present research demonstrated that QRHX dose-dependently decreased the myocardial infarct size; improved cardiac function; decreased the levels of myocardial enzymes, oxidative stress and apoptosis; and blocked the activity of caspase-3 and Bax/Bcl-2." (PMID 39664523, 2024). "This is in agreement with previous studies that have documented a reduction in cardiomyocyte apoptosis following DEX treatment in the context of myocardial infarction, as evidenced by an increase in the Bcl-2/Bax ratio, as well as in I/R-induced cardiomyocyte injury." (PMID 37430319, 2023). "The MST1-mediated BECLIN1 phosphorylation that enhances the BECLIN1:BCL-2 interaction to reduce autophagy also consequently reduces the interaction between BCL-2 and BAX, causing BAX activation and stimulation of apoptosis during myocardial infarction." (PMID 34204202, 2021). "The Bax/Bcl-2 ratio may serve as an independent predictive marker of the therapeutic response, and merits further examination, as the myocardial infarction with depression induced increase of the Bax/Bcl-2 ratio might enhance apoptosis of cardiomyocyte." (PMID 23394076, 2013). "In fact, Bcl-2 overexpression mediated the survival of human hematopoietic precursors during fetal life and prolonged the survival of myoblasts transplantation in acute myocardial infarction and chronic heart failure." (PMID 23150735, 2012). "Finally, at day 28 post surgery, salidroside administration largely decreased the cross-sectional area of myocardial fibers in myocardial infarction model mice, which was accompanied by the following changes in apoptosis markers: elevated levels of Bcl-2 and reduced Bax and cleaved caspase 3 levels." (PMID 40016840, 2025). "And also, It was reported that the over expressed Bcl-2 gene can protect MSCs against apoptosis under hypoxic conditions both in vitro and in vivo and the transplantation of the Bcl-2 gene engineered MSCs may improve heart functional recovery after acute myocardial infarction." (PMID 24955582, 2014). "In a rat model of acute myocardial infarction, Atractylodesin III reduces apoptosis of cardiomyocytes in acute myocardial infarction by decreasing the expression of Bax and CASP3, and up-regulating the ratio of Bcl-2 and Bcl-2/Bax." (PMID 38803438, 2024). "The results of this study primarily confirmed for the first time that luteolin could inhibit I/R-induced myocardial infarct size and LDH release, upregulate antiapoptosis protein Bcl-2, and downregulate proapoptosis proteins Bax and cleaved caspase-3." (PMID 26681967, 2015).
myocardial infarction (continued). "Moreover, the anti-apoptotic effects of exercise, such as increasing the BCL-2/Bax ratio and reducing apoptosis after acute myocardial infarction in non-obese mice, have recently been reported." (PMID 37711889, 2023). "The cardiac function indicators, myocardial infarct size, lactic dehydrogenase (LDH) release, mitochondrial ultrastructure, mitochondrial reactive oxygen species (ROS) generation rates, ATP content, protein expression of p-JAK, p-STAT3, Bcl-2 and Bax were measured." (PMID 28392989, 2017). "Additionally, nimbin treatment led to an elevation of Bcl-2 genes in the myocardial tissue, while simultaneously downregulating the expression of proapoptotic genes and apoptosis-related genes, Bax, caspase-3, −9 and cytochrome c in rats with ISO-stimulated myocardial infarction." (PMID 41329533, 2025).
thyroid cancer (64 papers, 1996 to 2025). "Among the endocrine types of thyroid cancer, thyroid cancer accounts for 1–2% of systematic cancers and is the most prevalent OA that causes apoptosis via the Bax/Bcl2 pathway." (PMID 39926108, 2025). "It has also been found to be differentially expressed between PTCs and normal tissues, and genetic variants in BCL2 could contribute to the risk of thyroid cancer." (PMID 24718460, 2014). "Besides, loss of BCL2 was associated with loss of differentiation in thyroid cancer." (PMID 31583243, 2019). "Therefore, local anesthetics alter the protein levels of key members of the Bcl-2 family in a manner that favors an increase in the ratio of Bax/Bcl-2, which may contribute to the susceptibility of thyroid cancer cells to apoptosis." (PMID 24586874, 2014). "To uncover the most distinct genes in different thyroid cancer subtypes, we screened BCL2, BHLHE40, MICAL2, TGM2, and TPO by comparing each pair of existing subtypes." (PMID 39872516, 2024). "Next, 131I deposition suppresses thyroid cancer proliferation by promoting cell cycle arrest and inhibiting BCL-2 expression." (PMID 36776316, 2023). "Revising the available literature, several studies reported that the expression of some inhibitors of Bcl-2 cell death was reduced in thyroid cancer patients, while inducers of Bax cell death increased in those patients." (PMID 35203561, 2022). "Our data demonstrate that KA kills thyroid cancer cell lines by inhibiting their glycolysis ability, the MAPK/ERK pathway and the Bcl-2 level and suggest that KA has potential clinical value in thyroid cancer therapy." (PMID 34264510, 2022). "Overexpression of Bcl-2 attenuates the inhibitory effects of overexpression of miR-15 on cell invasion and migration in thyroid cancer." (PMID 34980181, 2022). "There was a significant decrease in the gene expression of Bcl-2 in patients of stage I and II thyroid carcinoma compared with the control group." (PMID 35203561, 2022). "Herein, the expression of bax, bcl2, caspase-3 and caspase-8 genes of sw-1736 thyroid cancer cell line was examined after the incubation with 7 μl of the batch curcumin-niosome nanoparticles in 100 μl of cell culture media for 72 h." (PMID 34453618, 2021). "The proliferative effects of estrogen in thyroid cancer are mainly mediated through the regulation of bcl-2, Bax, and c-fos genes." (PMID 32426104, 2020). "IL-4 and IL-10 protect thyroid cancer cells from cytotoxic effect of antineoplastic drugs by induce the expression of Bcl-xL and Bcl-2." (PMID 32655554, 2020). "B-cell lymphoma-2 (Bcl-2), an oncogene expressed in most thyroid carcinomas, is also found to be a target of several different microRNAs." (PMID 33113852, 2020). "Next, we used the GEPIA database to analyze the predictive power of BCL2 for the clinical stage and survival of TCGA thyroid cancer." (PMID 31842912, 2019). "PV induced apoptosis by alteration of the Bcl-2/Bax ratio and activation of caspase-3 in thyroid carcinoma cells." (PMID 31354479, 2019). "It has been showed that low doses of paclitaxel enhanced Bcl-2 phosphorylation and led to its degradation and increasing Bax level and induced changes characteristic to apoptosis in human anaplastic cells in thyroid cancer cells." (PMID 29552052, 2017). "The proliferative effects of 17β-oestradiol (E2) in thyroid cancer were found to be mediated through the regulation of genes involved in growth control, such as bcl-2, Bax, and c-fos." (PMID 28717394, 2017). "In this study we showed the efficacy of the BH3 mimetic drug and pan-BCL-2 antagonist GX15-070 for cell death induction in thyroid carcinoma cells of various histological origins." (PMID 26198850, 2015).
thyroid cancer (continued). "In fact, the proliferative effects of E2 in thyroid cancer were found to be mediated through regulation of genes involved in growth control, such as bcl-2, Bax, and c-fos." (PMID 24222765, 2013). "H19 is generally upregulated in thyroid cancer tissues, and silencing H19 can increase the expression of the pro-apoptotic proteins, e.g., Bax and caspase-3, and decrease the expression of the anti-apoptotic protein, Bcl-2." (PMID 41154428, 2025). "Also, BCL2 expression confers protection to thyroid carcinomas by inhibiting apoptosis triggered by chemotherapy." (PMID 40804316, 2025). "Given that BCL2 is known to safeguard thyroid carcinomas against apoptosis induced by chemotherapy, the SS-BCL2-TC pathway could represent a detrimental effect of SS on the treatment of TC." (PMID 39928612, 2025). "Some researchers have found that BCL-2 might help thyroid cancer evade apoptosis, making it a suitable target for therapy." (PMID 39872516, 2024). "It is suggested that TREM2 exerts a pro-proliferative effect on thyroid cancer cells by activating the NF-κB signaling pathway to upregulate the expression of cyclin D1 and Bcl2, indicating that TREM2 may be located upstream of the NF-κB signaling pathway." (PMID 36438899, 2022). "The study also investigated the potential apoptotic and inflammatory mechanisms involved in thyroid cancer through the determination of B-cell lymphoma 2 (Bcl-2), interleukin-8 (IL-8) and tumor necrosis factor α (TNFα) during the different stages of the cancer using a series of molecular methods." (PMID 35203561, 2022). "Moreover, Bcl-2 is a direct target of miRNAs to participate in the development of human cancers, such as miR-15 in thyroid cancer, miR-448 in hepatocellular carcinoma, and miR-1915-3p in gastric cancer." (PMID 34980181, 2022). "Various studies showed that BTG1 overexpression suppressed proliferation, migration and invasion, and induced apoptosis and cell cycle arrest of lung, kidney, breast, esophageal, hepatocellular, nasopharyngeal, and thyroid cancers with Cyclin D1, Bcl-2, and MMP-9 hypoexpression." (PMID 33330092, 2020). "Besides, autocrine production of IL-4 and IL-10 induces the over-expression of Bcl-xL and Bcl-2, two anti-apoptotic proteins, which subsequently protect thyroid cancer cells from the cytotoxic effects of antineoplastic drugs." (PMID 32655554, 2020). "Therefore, the expression level of BCL2 can be used as a predictor of survival in patients with thyroid cancer." (PMID 31842912, 2019). "BCL2 was generally downregulated in tumor tissues, and this trend became more pronounced as the disease progressed, so BCL2 also has a potential to be a dynamic signal for estimating the progression and prognosis of thyroid cancer." (PMID 31842912, 2019). "Our findings suggested that aberrantly expressed BCL2 may have an unknown novel function as a potential tumor suppressor in thyroid cancer progression." (PMID 31583243, 2019). "In addition, we found that in TCGA thyroid cancer data, BCL2 was differentially expressed between cases and controls." (PMID 31842912, 2019). "VEGF-A could play a more important role in the progression of thyroid carcinoma through angiogenesis process than Notch1 or Bcl-2." (PMID 30544959, 2018). "Moreover, we examined Bcl-2 and Bax expression in thyroid cancer cells in response to PANDAR knockdown." (PMID 28507479, 2017). "Previous studies have suggested that the Bax gene may be related to the occurrence of thyroid cancer; Bcl-2 plays a prominent role in determining the threshold of apoptotic sensitivity." (PMID 29212221, 2017).